CKS1B (CDC28 protein kinase regulatory subunit 1B)
Diseases named in the same sentence as CKS1B in open-access papers (continued):
Sharing a sentence is not in itself a finding about the gene and the disease.
neuroblastoma (2 papers, 2015 to 2020). Neuroblastoma (NB) is the most common solid, extracranial childhood tumor. "A genome-wide, drop-out shRNA screen carried out in our laboratory has identified CKS1B as a potential therapeutic target gene in MYCN-amplified neuroblastoma by inducing synthetic lethality." (PMID 31900399, 2020). "Cocktails of small molecule inhibitors of CKS1B, AHCY, BLM, and PKMYT1 profoundly affected the growth of all neuroblastoma cell lines but selectively caused death of MYCN-amplified cells." (PMID 25477524, 2015). "The significance of BLM, AHCY, PKMYT1, and CKS1B in the pathogenesis of neuroblastoma is indicated by their elevated expression in MYCN-amplified tumor samples and in MYCN-overexpressing cells and their correlation with poor patient survival." (PMID 25477524, 2015).
Sepsis (2 papers, 2022). Sepsis is defined as life-threatening organ dysfunction caused by a dysregulated host response to infection. "In summary, the present study identified SIGLEC9, TSPO, CKS1B, and PTTG3P as the genetic biomarkers and established a four-gene-based model for the effective diagnosis and risk prediction of sepsis/se-ARDS based on gene co-expression network." (PMID 35844622, 2022). "Further correlation analysis based on SIGLEC9, TSPO, CKS1B, and PTTG3P was carried out to identify the potential interactions and effects of these diagnostic biomarkers during sepsis/se-ARDS development." (PMID 35844622, 2022). "Afterwards, a sepsis/se-ARDS risk nomogram model that involves SIGLEC9, TSPO, CKS1B, and PTTG3P as the independent predictors was constructed." (PMID 35844622, 2022). "Moreover, the levels of immune cell infiltration in the progress of sepsis/se-ARDS promoted their further correlation analysis based on SIGLEC9, TSPO, CKS1B, and PTTG3P, the diagnostic biomarkers identified in the study." (PMID 35844622, 2022). "The expressions of four genes were remarkably related to each other, and it is apparent that the highly positive correlations between SIGLEC9 and TSPO and between CKS1B and PTTG3P were spectacularly remarkable at all the stages of sepsis/se-ARDS progression." (PMID 35844622, 2022). "During the development of sepsis/se-ARDS, the expressions of the identified biomarkers including SIGLEC9, TSPO, CKS1B and PTTG3P were all regulated remarkably and generally exhibited notable correlations with the stages of sepsis/se-ARDS." (PMID 35844622, 2022). "Both SIGLEC9 and TSPO were significantly upregulated on sepsis day 0 and then descended a bit more on sepsis day 7 (***P<0.001) during sepsis development, while both CKS1B and PTTG3P appeared to be steadily upregulated on sepsis day 0 and day 7 (*P<0.05)." (PMID 35844622, 2022). "Besides, SIGLEC9, TSPO, CKS1B and PTTG3P were considerably correlated with the infiltration of various immune cells including neutrophils and monocytes during sepsis/se-ARDS." (PMID 35844622, 2022). "SIGLEC9, TSPO, CKS1B, and PTTG3P all exhibited remarkable changes of upregulations in the sepsis group compared with control group in both datasets with P<0.05 (except for CKS1B in GSE28750), which proved the great diagnostic and predictive performance of these four biomarkers." (PMID 35844622, 2022).
acute myeloid leukemia (1 paper, 2021). Acute myeloid leukemia (AML) is a group of neoplasms arising from precursor cells committed to the myeloid cell-line differentiation. "More specifically, CKS1B was remarkably higher in all 26 tumors than normal tissues, except KICH (kidney chromophobe), LAML (acute myeloid leukemia), and PRAD (prostate adenocarcinoma)." (PMID 34845438, 2021).
adrenocortical carcinoma (1 paper, 2021). "Moreover, reduced CKS1B methylation was observed in certain tumors, for example, adrenocortical carcinoma." (PMID 34845438, 2021). "In addition, with the help of “Pathological Stage Plot” module of GEPIA2, we observed increased expression of CKS1B in most tumors with disease progression, especially in ACC (adrenocortical carcinoma), KICH, and KIPR (kidney renal papillary cell carcinoma)." (PMID 34845438, 2021).
colon carcinoma (1 paper, 2019). "In this context, it is not surprising to observe that expression of CDK1, CDK2, and cyclin B2 (CCNB2), which have close functional interactions with an oncogenic protein CKS1B, was significantly increased in colon cancer samples in the TCGA data set." (PMID 31717435, 2019).
dementia (1 paper, 2023). Loss of intellectual abilities interfering with an individual's social and occupational functions. "Five autoantibodies in particular, were dysregulated in dementia and MCI, including CAMK2A, CKS1B, ETS2, MAP4, and NUDT2." (PMID 38107644, 2023). "Five autoantibodies (CAMK2A, CKS1B, ETS2, MAP4, and NUDT2) were dysregulated in both dementia and MCI." (PMID 38107644, 2023). "Five autoantibodies were commonly dysregulated in both dementia and MCI, including anti-CAMK2A, CKS1B, ETS2, MAP4, and NUDT2." (PMID 38107644, 2023). "Whilst, CKS1B (CDC28 protein kinase regulatory subunit 1B) plays a role in cell cycle regulation and has been found to be dysregulated in several types of cancer, there is limited research on its potential involvement in dementia." (PMID 38107644, 2023).
diabetes (1 paper, 2020). "In addition, we identified nine genes (CABIN1, CKS1B, C19orf60, SDR39U1, SLC31A1, DNAJA4, ZC3H8, OTUD3 and UBALD1) not previously associated with diabetes, but that are known to be involved in processes potentially linked to β-cell dysfunction, such as cell turnover, oxidative stress and ER stress." (PMID 33575641, 2020).
glioblastoma multiforme (1 paper, 2021). "Moreover, high CKS1B expression was even meant better OS in KIRC (kidney renal clear cell carcinoma) (p = 0.026) and better DFS in GBM (glioblastoma multiforme) (p = 0.046)." (PMID 34845438, 2021).
lymphoid neoplasm (1 paper, 2019). A neoplasm composed of a lymphocytic cell population which is usually malignant (clonal) by molecular genetic and/or immunophenotypic analysis. "dup(1q)/gain of CKS1B, del(6q)/deletion of MYB, and del(9p)/deletion of CDKN2A, which are common in lymphoid neoplasms, were detected at a low frequency in adult B‐ALL patients with hyperdiploidy." (PMID 31173486, 2019).
Obesity (1 paper, 2022). Accumulation of substantial excess body fat. "Cyclin-dependent kinases (CKs) (i.e., CKS1B, CKS2) are also involved with cell cycle regulation, and inhibitors of CKs have drawn attention to their use in controlling diet-induced obesity." (PMID 36291149, 2022).
oral squamous cell carcinomas (1 paper, 2017). "CKS1B overexpression is correlated with low p27 expression and adverse survival in several human malignancies including gastric, colorectal, and oral squamous cell carcinomas because of its critical role as a cell cycle regulator and its involvement in various human carcinomas." (PMID 28385156, 2017).
osteosarcoma (1 paper, 2021). A usually aggressive malignant bone-forming mesenchymal neoplasm, predominantly affecting adolescents and young adults. "CDC28 Protein Kinase Regulatory Subunit 1B (CKS1B) is a member of cyclin-dependent kinase subfamily and the relationship between CKS1B and osteosarcoma (OS) remains to be explored." (PMID 34925510, 2021).
pancreatitis (1 paper, 2025). Inflammation of the pancreas. "Further analysis of RNA-sequencing dataset GSE132326 demonstrated that CKS1B expression progressively increased during the transition from pancreatitis to PDAC, particularly in the context of Kras mutations and inflammation." (PMID 39897042, 2025). "Analysis of single-cell and RNA-sequencing datasets and our various mouse models revealed progressive CKS1B upregulation from pancreatitis to PDAC, suggesting its potential as a biomarker for early disease detection." (PMID 39897042, 2025).
thymoma (1 paper, 2021). A neoplasm arising from the epithelial cells of the thymus. "To confirm this hypothesis, we did a series of comparisons by TIMER and GEPIA2 databases and observed a statistically positive correlation between CKS1B expression and CAFs infiltration in ACC, KICH, and KIRP, but a negative correlation in BRCA, LUAD, LUSC, STAD, and THYM (thymoma)." (PMID 34845438, 2021).
viral infection (1 paper, 2019). "A subset of genes including OAS1, OAS2, EFNB2, and CKS1B involved in the immune response to viral infection showed a higher expression level and H3K4me3 enrichment in PEDV-infected samples, suggesting the role of H3K4me3 deposition in promoting their expression." (PMID 31382472, 2019).
tumor (48 papers, 2004 to 2025). "We then investigated the potential association between CKS1B alteration and survival outcomes in tumor patients." (PMID 34845438, 2021). "Our first pan-cancer analysis of CKS1B demonstrated a statistical association between CKS1B and tumor clinical prognosis, immune cell infiltration, DNA methylation, tumor mutation burden, and microsatellite instability across multiple tumors." (PMID 34845438, 2021). "Here, we also found that CKS1B was frequently upregulated in CRC tumor tissues compared with normal tissues and that a high level of CKS1B expression was associated with poor overall survival in CRC patients." (PMID 31717435, 2019). "This suggests that the increased nucleotide biosynthesis associated with CKS1B+ neoplasm may bolster rapid tumour cell proliferation and foster resistance to chemotherapeutic regimens." (PMID 38946232, 2024). "Studies have shown that high expression of CKS1B may be associated with abnormal proliferation of tumour cells, malignant transformation, invasiveness, and prognosis." (PMID 39046884, 2024). "Moreover, we analyzed the association between CKS1B and expression of TILs, immunosuppressive factors, and immunostimulatory factors in tumor microenvironment." (PMID 34845438, 2021). "Overexpression of CKS1B reversed the suppressed tumor growth, migration and CSCs self-renewal observed in FOXM1-knockdown cells compared to their control counterparts." (PMID 39897042, 2025). "CKS1B knockdown significantly reduced the self-renewal capacity and number of CSCs, as evidenced by in vitro tumor sphere formation, increased CD44+CD24+/CD133+ cell populations, and decreased expression of CSCs markers (ABCG2, C-MYC, ALDH1, BMI-1)." (PMID 39897042, 2025). "Knockdown of CKS1B significantly reduced tumor growth rate and overall tumor weight compared to the control groups." (PMID 39897042, 2025). "Conversely, knocking down CKS1B in BxPC-3 and CFPAC-1 cells overexpressing FOXM1 demonstrated that CKS1B knockdown reversed the enhanced tumor growth, migration, and CSCs self-renewal associated with FOXM1 overexpression." (PMID 39897042, 2025). "Further analysis revealed that CKS1B expression patterns in LUAD and LUSC were significantly associated with key clinical features such as tumor histology, patient demographics (e.g., race, gender, age, smoking status), and nodal metastasis." (PMID 40165937, 2025). "The results showed the expression of tumor malignant characteristic genes such as CDKN2A CKS1B, HSPA9, IDH2, and MYC among different subpopulations of plasma cells, with high expression in plasma cell_2." (PMID 39271659, 2024). "Utilizing the scMetabolism R package to analyse metabolic heterogeneity within tumour cell subgroups, we observed significant metabolic reprogramming in CKS1B+ neoplasm." (PMID 38946232, 2024). "Leveraging marker genes from the CKS1B+ tumour cell cluster, we employed machine learning algorithms to establish a prognostic and immunotherapeutic signature (PIS) for LUAD." (PMID 38946232, 2024). "Focusing on CKS1B+ neoplasm, we explored its spatial localization, finding that these cells primarily concentrated in the core areas of the tumour cells." (PMID 38946232, 2024). "Using marker genes of CKS1B+ neoplasm, we developed a prognostic and immunotherapy‐related signature (PIS) through a machine learning combinatorial algorithm." (PMID 38946232, 2024). "Subsequently, utilizing machine learning techniques, we constructed the PIS model, comprising marker genes of CKS1B+ tumours (RHOV, ANLN, DEAR, PSMB7, KRT8, LDHA)." (PMID 38946232, 2024).
tumor (continued). "Both BisqueRNA and GSVA algorithms indicated a progressive increase in the abundance of CKS1B+ tumour cell populations from partial response/complete response (PR/CR) to SD and then to PD." (PMID 38946232, 2024). "Regarding OS, the abundance of CKS1B+ neoplasm demonstrated strong prognostic value in both immunotherapy and chemotherapy cohorts (HR >1, p < 0.05)." (PMID 38946232, 2024). "CKS1B+ neoplasm is at the initial stage of development, gradually decreasing over time, whereas MIF+ neoplasm is at the terminal stage, increasing as time progresses." (PMID 38946232, 2024). "This is corroborated by our preceding findings: the abundance of CKS1B+ neoplasm is inversely correlated with the degree of pathological remission in chemotherapy patients." (PMID 38946232, 2024). "To better elucidate the value of CKS1B in predicting immunotherapy response, we analyzed the tumor immune dysfunction and exclusion (TIDE) score in PAAD patients of TCGA." (PMID 36405738, 2022). "Cyclin-dependent kinase regulatory subunit 1B (CKS1B) is crucial in cell cycle regulation and closely related to tumor initiation, maintenance, and progression, thus significantly associated with the prognosis of cancers." (PMID 35844622, 2022). "Mechanistic investigations demonstrated that the miR-197-mediated CKS1B/STAT3 axis was excavated exerting tumor progression regulated by various protooncogenes like BCL2 Apoptosis Regulator (BCL2), MYC, and Cyclin D1(CCND1)." (PMID 34925510, 2021). "In cases of ACC, we found CKS1B methylation was significantly lower in tumor tissues than adjacent normal tissues." (PMID 34845438, 2021). "We first analyzed basal expression levels of CKS1B in different blood cells, tumor cell lines, and tumor tissues using Consensus database." (PMID 34845438, 2021). "The mechanism by which CKS1B and CAFs affect tumor microenvironment will be an interesting research direction." (PMID 34845438, 2021). "Some investigations have revealed that a miR-197-mediated CKS1B/STAT3 axis exerts a role in tumor progression, which is regulated by different genes, such as Bcl-2, c-Myc, and cyclin D125." (PMID 34907223, 2021). "Methylation analysis result in ACC demonstrated that CKS1B methylation was significantly lower in tumor than corresponding normal tissues." (PMID 34845438, 2021). "Mechanistic studies have shown that the miR-197-mediated CKS1B/STAT3 axis plays a role in tumor progression and is regulated by multiple oncogenes (Bcl-2, c-Myc, and cyclin D1) and that PD-L1 is a putative biomarker of this axis." (PMID 33102238, 2020). "In summary, gC1qR suppressed the MM-inhibiting role of C1q and regulated CKS1B mRNA in promoting tumor proliferation via IGF2BP3 in 1q21-amplified MM." (PMID 32760394, 2020). "This study provides novel evidence that gC1qR can suppress the tumor-inhibiting role of C1q and regulate CKS1B mRNA through IGF2BP3 in MM patients with Amp1q21." (PMID 32760394, 2020). "Increased CKS1B expression is involved in tumor initiation, maintenance, and progression and positively correlated with poor prognosis." (PMID 33102238, 2020). "Here, we present experimental evidence showing that miR-1258 plays a tumor-suppressive role by directly regulating the expression of the oncogenic CKS1B gene in CRC." (PMID 31717435, 2019). "In CRC, miR-1258 expression also decreased cell proliferation and migration in vitro and tumor growth in vivo, similar to cells with silenced CKS1B expression." (PMID 31717435, 2019). "Consistently, increased CKS1B levels in tumor samples were also observed in other human cancer data sets, such as the TCGA cohort." (PMID 31717435, 2019). "Studies suggest an miR-197-induced regulating mechanism of PD-L1 in tumor cells via the miR-197/CKS1B/STAT3 pathway in non-small cell lung cancer (NSCLC)." (PMID 29029502, 2017). "In the NSCLC study, the miR-197/CKS1B/STAT3-induced PD-L1 network leads to tumor progression, and miR-197 is an inverse indicator of PD-L1 expression and predicts shorter OS." (PMID 29029502, 2017).